TERT (telomerase reverse transcriptase)
Diseases named in the same sentence as TERT in open-access papers (continued):
Sharing a sentence is not in itself a finding about the gene and the disease.
glioblastoma (continued). "In the 2021 WHO CNS, glioblastoma is defined as a tumor with obligatory wildtype IDH1/2, characterized by diffuse astrocytic histology and at least one of the following features: necrosis, microvascular proliferation, gain of chr 7 and loss of chr 10, EGFR amplification, or TERT mutation." (PMID 39684714, 2024). "Moreover, the complex formed by ETS1 with p52 NF-κB, whose expression is specifically controlled by non-canonical NF-κB signalling, has been shown to bind selectively the mutant TERT promoter −146A thus promoting telomerase expression in glioblastoma and melanoma." (PMID 38033865, 2023). "Only TERT mutations have been more frequently observed among patients with early progression; however, prior reports found no prognostic relevance of the TERT promotor status in glioblastoma patients when other diagnostic hallmarks have been fulfilled (as in our series)." (PMID 36980633, 2023). "Furthermore, TERT promoter mutation status is of prognostic significance not only in diffuse gliomas with non-glioblastoma histology, but also in glioblastoma." (PMID 34558656, 2022). "Eighty patients showed glioblastoma (GBM)-like features: IDH1 and 2 wild types (wt) and imbalance of chromosome 7 and chromosome 10q loss of heterozygosity, or telomerase reverse transcriptase (TERT) promoter mutation, or epidermal growth factor receptor (EGFR) amplification." (PMID 36176387, 2022). "In addition, it should be noted that IDH-wild-type diffuse astrocytic tumors in adults, if microvascular proliferation or necrosis or TERT promoter mutation or EGFR gene amplification or +7/−10 chromosome copy number changes are present, should be diagnosed as IDH-wild-type glioblastoma." (PMID 35153659, 2021). "We do not intend to analyze here the meaning of the title of the article “Could We Address the Interplay Between CD133, Wnt/β-Catenin, and TERT Signaling Pathways as a Potential Target for Glioblastoma Therapy?” by Behrooz and Syahir published recently in Frontiers in Oncology [issue April 1, 2021]." (PMID 34476215, 2021). "However, another recent study on spinal cord gliomas described three cases harboring TERT promoter mutations, suggesting that these do occur in spinal glioblastoma, though probably at a lower frequency than in non-spinal glioblastoma." (PMID 34193285, 2021). "Moreover, in IDH-wildtype diffuse astrocytic gliomas the presence of one or more of three genetic parameters (EGFR gene amplification, TERT promoter mutation, 7+/10−) appears to be adequate to assign the highest CNS WHO grade and classify them as glioblastoma-wildtype." (PMID 34638714, 2021). "Therefore, TERT may be involved in the progression and used for analyzing prognosis of glioblastoma." (PMID 33763172, 2021). "cIMPACT-NOW Update 3 recommended TERT promoter mutations as one of the three criteria (the other two being either EGFR amplification or combined whole chromosome 7 gain/chromosome 10 loss) to diagnosis “Diffuse astrocytic glioma, IDH-wildtype, with molecular features of glioblastoma, WHO grade IV”." (PMID 33228806, 2020). "TPMs have also been found to be associated with increased telomerase activity in primary glioblastoma (GBM) patient samples as well as in urothelial and GBM cell lines (comparison between wild type vs mutant TERT promoter)." (PMID 32674474, 2020). "Critically, since TERT promoter mutations occur in a vast majority of molecularly defined (i.e. IDH-mutant and 1p/19q-codeleted) oligodendrogliomas, assessment of 1p/19q status and exclusion of an IDH mutation by sequencing is usually required before designating a molecular glioblastoma." (PMID 30967140, 2019). "However, more recent reports have shown that this SNP has a negative effect in glioblastoma and liver cancer patients bearing activating TERT promoter mutations." (PMID 29100407, 2017).
glioblastoma (continued). "In combination with loss of nuclear ATRX expression, IDH1, 1p/19q and TERT promoter mutations define the most frequent type of infiltrative astrocytoma, while mutations in the EGFR gene (seen in 35 % of all cases of glioblastoma) are associated with primary glioblastoma." (PMID 26839018, 2016). "Strikingly, TERT promoter mutations are not unique to melanomas, but have been later found to be frequent in many other malignancies such as hepatocellular carcinoma, bladder cancer, and glioblastoma." (PMID 27792139, 2016). "The prognostic impact of TERT mutations has been controversial in IDH-wild tumors, particularly in glioblastomas (GBM)." (PMID 27503138, 2016). "Similarly, patients whose tumors harbored TERT mutations tended to be much older and their tumors also frequently showed EGFR alterations, again more consistent with elderly populations harboring primary glioblastoma." (PMID 26244119, 2015). "According to the WHO Classification 2021, Glioblastoma is categorized as a grade IV tumor, with specific molecular alterations (IDH‐wildtype, TERT, EGFR, chromosome +7/−1)." (PMID 40498413, 2025). "In glioblastoma models involving mice and pigs, FUS has been shown to increase ctDNA levels, enabling improved sensitivity of biomarkers such as EGFR and TERT as well as enhanced detection of green fluorescent protein (eGFP)." (PMID 39796751, 2025). "In the CNPI, this means editing genes such as SCN1A, DEPDC5, or KCNQ2 in focal epilepsy, or IDH1, TERT, or PTEN in glioblastoma, while also ensuring specificity and limiting collateral damage to the patient." (PMID 40806492, 2025). "In glioblastoma multiforme (GBM) cells, the NF-κB signal pathway selectively induces TERT expression with mutant TERT promoters, which is due to the p52-binding sites formation after specific mutation in TERT promoters." (PMID 38278800, 2024). "Patients with de novo glioblastomas with a methylated MGMT promoter benefited from temozolomide, whereas those with TERT unmethylated mutant-MGMT had a poorer prognosis." (PMID 39586842, 2024). "Diffuse astrocytic tumours lacking the histological features of glioblastoma are designated molecular GBM (molGBM, WHO grade 4) if they exhibit specific molecular abnormalities, such as TERT promoter mutation, EGFR amplification, or chromosomal + 7/− 10 copy changes." (PMID 38890658, 2024).
glioblastoma (continued). "Finally, our analyses are extended to additional cancer entities from the Pan-Cancer Analysis of Whole Genomes (PCAWG) cohort and glioblastoma (GBM) to determine the signaling pathways co-regulated with TERT across entities." (PMID 37418389, 2023). "Among 1008 IDH-wildtype glioblastomas WHO grade 4, TERT promotor status was available in 466 patients including 396 individuals with (IDHwt/TERTmut) and 70 patients without TERT promotor mutations (IDHwt/TERTwt)." (PMID 36325373, 2022). "For example, eribulin (a microtublublin inhibitor with specific activity against TERT-RNA-dependent RNA polymerase), imetelstat (a TERT inhibitor), and BIBR1532 (a potent telomerase inhibitor) have showed promising results with glioblastoma cell lines." (PMID 35436952, 2022). "STAT3 has a key role in the expression of TERT in HCC, breast and glioblastoma where STAT3 expression levels correlated with TERT expression." (PMID 33802026, 2021). "Consequently, “Glioblastoma, IDH-wildtype” in adults should be diagnosed in the setting of an IDH-wildtype diffuse and astrocytic glioma if there is either microvascular proliferation, or necrosis, or TERT promoter mutation, or EGFR gene amplification, or +7/−10 chromosome copy number changes." (PMID 35008238, 2021). "We aimed to evaluate the clinical outcomes of molecular glioblastoma (mGBM) as compared to histological GBM (hGBM) and to determine the prognostic impact of TERT mutation, EGFR amplification, and CDKN2A/B deletion on isocitrate dehydrogenase (IDH)-wildtype GBM." (PMID 33235995, 2020). "In one case (TERT), the same MPRA library was used for experiments in two different cell types (HEK293T and a glioblastoma cell line)." (PMID 31395865, 2019). "Similar conclusions were reached in another study showing that TERT promoter mutant IDH-WT astrocytomas and glioblastomas have a poorer prognosis than TERTpWT tumors." (PMID 30279357, 2018). "Currently, glioblastoma STS can to some extent be identified using molecular markers e.g. IDH, MGMT, and TERT." (PMID 29136645, 2017). "Apart from IDH mutant tumors, the survival curves of glioblastoma in the Eckel-Passow study are very similar, with IDH wild-type tumors performing poorly (particularly the TERT mutant subset)." (PMID 26244119, 2015). "In addition, higher expression levels of MMP9, TERT, VEGFA, ZDHHC18, CHEK2, and ADM elevate the probability of predicting glioblastoma." (PMID 40867242, 2025). "At the molecular level, GBM is characterized by the absence of isocitrate dehydrogenase (IDH) gene mutations (glioblastoma, IDH-wild type) and specific genetic alterations in the TERT promoter, chromosomes 7/10, and the EGFR gene." (PMID 40076445, 2025). "These cytogenomic methods revealed classical findings associated with glioblastoma, such as a lack of IDH and TERT mutations, gain of chromosome 7, and loss of chromosome 10." (PMID 39534304, 2024). "Only three patients who had both EGFR and TERT data did not have the molecular characteristics of glioblastoma." (PMID 38672254, 2024). "No additional alterations were suggestive of IDH-wild-type glioblastoma (EGFR amplification, TERT promoter mutation, or simultaneous gain of chromosome 7/loss of chromosome 10) were detected." (PMID 37324217, 2023). "In particular, compared with tumors without TERT mutations, IDH wild-type glioblastomas with TERT mutations have a greater number of neutrophils with marked expression of the cytokines CXCR2, CXCR4, CCL2, CCL5 and MMP9." (PMID 38275375, 2023). "Several studies in TERT-mutant glioblastomas demonstrated that GABPA, an ETS factor acting as a tetrameric protein along with its GABPB isoform, drives TERT-mutant transcription in this tumor lineage, opening the door to targeting the GABPA/GABPB axis to achieve TERT downregulation in that context." (PMID 35053525, 2022).
glioblastoma (continued). "The lack of radiation dose response in TERTwt patients but not TERTmut patients also suggests that observations of dose response sensitivity in IDHwt glioblastomas may be dependent on particular genetic alterations, such as CDKN2A and TERT." (PMID 36380219, 2022). "There is also evidence that the absence of EGFR amplification, TERT promoter mutation, and + 7/− 10 is associated with a better clinical course in tumors that qualify as IDH-wildtype glioblastoma by histologic features alone." (PMID 35978439, 2022). "The ADC values are used as a potential marker for predicting MGMT and TERT status in glioblastomas; however, without expert consensus." (PMID 36471242, 2022). "We did therefore not find evidence that TERT promotor status adds prognostic information in IDH-wildtype glioblastomas exhibiting classical histopathological hallmarks (or other mutations) sufficient for glioblastoma diagnosis." (PMID 36325373, 2022). "However, it is now recognized that glioblastomas (GBM) occurring in pediatric and adult patients are genetically distinct: EGFR, TERT, and PTEN mutations are often seen in adult patients, whereas NTRK, H3K27M, H3G34R, and H3G34V mutations are commonplace in pediatric patients." (PMID 36072789, 2022). "GBMs decreases GABPB1 and GABPB1L mRNA levels and it could be used as a potential therapeutical approach together with targeting therapy in TERT and GABP dependent glioblastomas." (PMID 34194624, 2021). "Between the primary and secondary glioblastomas with and without chemotherapy treatment, TERT is significantly elevated in the prim." (PMID 34194624, 2021). "Between primary and secondary glioblastomas with and without chemotherapy, TERT is elevated in the former while GABPB1 is increased in the secondary glioblastomas." (PMID 34194624, 2021). "The non-invasive detection of a mutant TERT promoter is especially attractive and has been evaluated in plasma, urine and cerebrospinal fluid (CSF) for the diagnosis/monitoring of HCC, bladder cancer and glioblastoma, respectively." (PMID 31285550, 2019). "In contrast, restoration of the promoter mutation to the wild-type sequence or depletion of GABPA in melanoma and glioblastoma cell lines enables silencing of the histone mark, suggesting that GABPA binding to TERT promoter is a key step to change the chromatin status." (PMID 30709063, 2019). "This shows that activation of noncanonical NF-κB can support tumor growth of some glioblastoma by upregulating TERT expression." (PMID 29874793, 2018). "However, the wild-type IDH1/2 contradicts compatibility with a high-grade astrocytoma or oligodendroglioma, and the absence of TERT mutation and EGFR amplification does not align well with glioblastoma." (PMID 41323387, 2025). "However, the tumor lacked TERT promoter mutation, EGFR amplification, and polysomy 7/monosomy 10, which are the characteristic genetic alterations of IDH-wild-type glioblastoma in adult patients." (PMID 39335555, 2024). "However, these tumors did not exhibit the key molecular alterations of glioblastoma, IDH-wildtype such as TERT promoter mutation, EGFR amplification, or chromosome 7 gain and 10 loss." (PMID 38605367, 2024). "Furthermore, the tetrameric complex GABPA/GABPB plays an important role in the regulation of TERT transcription since it selectively binds and activates the mutant but not the wild-type TERT promoter in glioblastoma." (PMID 38033865, 2023). "To date, TERT should not be considered a prognostic factor in glioblastoma." (PMID 38201248, 2023).
glioblastoma (continued). "Tumor PGBM underwent extensive histopathological and genomic analysis for clinical purposes and demonstrated diffuse and high-grade glioblastoma histology, IDH1 mutation (IDH1 c.395G>A [p.Arg132His]), MGMT promoter methylation profile, TERT promoter wild-type, and absence of 1p/19q codeletion." (PMID 37192626, 2023). "To date, there are no approved TERT promoter glioblastoma therapies." (PMID 35436952, 2022). "Next, we measured TERT mRNA by RT-qPCR and like the RNAscope result, TERT was expressed in the tumor tissue but not in the adjacent “normal” FFPE punches and greater than or equal to FFPE punches obtained from a separate glioblastoma case with the hotspot mutation G228A." (PMID 36114166, 2022). "Another aspect of TERT promoter mutation is that this alteration without accompanying IDH mutation suggests clinically and biologically aggressive characteristics comparable with those of glioblastomas when found in histologically diagnosed as diffuse gliomas." (PMID 33228806, 2020). "An inverse correlation between relative telomere length and TERT expression in this study was in accorandance with an earlier report that showed shorter telomere length in gliobastoma that were positive for TERT expression and telomerase activity than those glioblastoma that were negative for both." (PMID 25797251, 2015). "Lowest survival in patients with only TERT promoter mutations and longest survival for patients with both TERT promoter and IDH mutations are most likely indicative of primary glioblastoma and oligodendroglial histologies, respectively, rather than any direct biological effect of the altered genes." (PMID 25797251, 2015). "In this review, we will examine the ongoing challenges of glioblastoma treatment and identify immunotherapeutic approaches that could treat glioblastoma, including Isocitrate dehydrogenase (IDH), Epidermal Growth Factor Receptor (EGFR), and Telomerase reverse transcriptase (TERT) peptide vaccines." (PMID 38932383, 2024). "If current recommendations for the adult setting were to be applied, the presence of TERT promoter mutation in combination with an absence of IDH1/IDH2 mutation would be compatible with a diagnosis of diffuse astrocytic glioma, with molecular features of glioblastoma, WHO grade IV." (PMID 32493417, 2020). "In IDH-wildtype adult diffuse gliomas, TERT promoter and EGFR amplifications are glioblastoma-defining events, even without necrosis or microvascular proliferation." (PMID 41567539, 2025). "We observed that, unlike in other TPM-carrying cancers such as glioblastomas, ETS factor GABPA does not unambiguously regulate transcription from the TERT mutant promoter in thyroid specimens." (PMID 35053525, 2022). "PriGO8A cells were isolated from a glioblastoma patient under conditions that preserve neural stem cell–like characteristics and are PTEN-null, C250T TERT promoter mutant, and without EGFR amplification." (PMID 34624316, 2021).